PTPN14 (protein tyrosine phosphatase non-receptor type 14)
Description:
Protein tyrosine phosphatase which may play a role in the regulation of lymphangiogenesis, cell-cell adhesion, cell-matrix adhesion, cell migration, cell growth and also regulates TGF-beta gene expression, thereby modulating epithelial-mesenchymal transition. Mediates beta-catenin dephosphorylation at adhesion junctions. Acts as a negative regulator of the oncogenic property of YAP, a downstream target of the hippo pathway, in a cell density-dependent manner. May function as a tumor suppressor.
Synonyms: PEZ; PTPD2; CATLPH; PTP36
Tractability: PROTAC: UniProt records ubiquitination sites on it; ubiquitination databases record sites on it; a small molecule that binds it is known.
Target class: Tyrosine protein phosphatase; Enzyme; Phosphatase; Protein Phosphatase
Gene: Protein-coding gene on chromosome 1 (214,348,700 to 214,552,449, reverse strand). Ensembl gene ENSG00000152104.
Subcellular location: Cytoplasm; Cytoplasm, cytoskeleton; Nucleus
Subcellular location (Human Protein Atlas): Nucleoplasm
Pathways (Reactome):
Immune System: Interleukin-37 signaling
Gene Ontology:
Molecular function: protein binding; protein tyrosine phosphatase activity; receptor tyrosine kinase binding; transcription coregulator activity
Biological process: lymphangiogenesis; negative regulation of cell population proliferation; regulation of protein export from nucleus; positive regulation of hippo signaling; protein dephosphorylation
Cellular component: cytoplasm; nucleoplasm; nucleus; cytoskeleton
Genetic constraint (gnomAD): Loss-of-function variants: 48 observed, 116.77 expected, observed/expected ratio (o/e) 0.41, 90% interval 0.32 to 0.52. The upper end of that interval is the gene's LOEUF score, 0.52, which puts it in group 2 of 6, group 1 being the genes least tolerant of losing a copy. Missense variants: 1,223 observed, 1,542.4 expected, observed/expected ratio (o/e) 0.79, 90% interval 0.76 to 0.83. Synonymous variants: 616 observed, 597.08 expected, observed/expected ratio (o/e) 1.03, 90% interval 0.96 to 1.1.
Homologues: Orthologues: chimpanzee PTPN14 (99% identical), macaque PTPN14 (99% identical), dog PTPN14 (96% identical), pig PTPN14 (95% identical), rabbit PTPN14 (93% identical), rat Ptpn14 (92% identical), mouse Ptpn14 (92% identical), guinea pig PTPN14 (89% identical), tropical clawed frog ptpn14 (68% identical). Paralogues in human: PTPN21 (54% identical), PTPRS (19% identical), PTPRD (19% identical), PTPRF (18% identical), PTPRB (17% identical), PTPRZ1 (15% identical), PTPRT (15% identical), PTPRM (15% identical), PTPN23 (15% identical), PTPRJ (14% identical), PTPN4 (14% identical), PTPRK (14% identical), and 23 more.
Diseases named in the same sentence as PTPN14 in open-access papers:
PTPN14 is named in the same sentence as 52 diseases in open-access papers, as found by Europe PMC text mining. Sharing a sentence is not in itself a finding about the gene and the disease. The quoted sentences say what the papers report.
breast carcinoma (15 papers, 2015 to 2024). "PTPN14 mutations have been identified in a variety of human malignancies, including breast cancer, colon cancer, and skin basal cell carcinoma, and thus PTPN14 has been implicated as a putative tumor and metastasis suppressor." (PMID 35135548, 2022). "Multiple somatic PTPN14 mutations have been associated with breast cancer, colon cancer and skin basal cell carcinoma suggesting an additional tumour suppressive role in preventing over-activation of the Hippo pathway in these cancer types." (PMID 33710332, 2021). "Studies have shown that PTPN14 has mutations in breast cancer, colon cancer, and other tumors." (PMID 34712552, 2021). "Moreover, the ability of PTPN14 to suppress breast cancer cell metastasis in experimental animal models was linked to a reduction in protein trafficking through the secretory pathway." (PMID 32152405, 2020). "In contrast to the effect of PTPN14 depletion, PTPN14‐overexpressing (PTPN14‐OE) breast cancer cells displayed diminished proliferation when cultured in monolayers, as evidenced by the results of the CCK‐8 and colony formation assays." (PMID 39189475, 2024). "Taken together, the results of the in vitro experiments suggest that the PTPN14 knockout enhances anoikis resistance, while the in vivo experiments confirm that the PTPN14 knockout promotes tumorigenicity in breast cancer cells." (PMID 39189475, 2024). "After culturing the cells under ULA conditions for 12 h, the phosphorylation levels of AKT Ser473 and ERK1/2 in PTPN14‐OE breast cancer cells were lower than those of the control group cells." (PMID 39189475, 2024). "Mechanistically, PTPN14 is identified as a key factor in dephosphorylating breast cancer antiestrogen resistance 3, a novel substrate, leading to the subsequent inhibition of PI3K/AKT and ERK signaling pathways." (PMID 39189475, 2024). "The results indicated significant differences in the expression levels of PTPN14 among these three types of tissues, with normal breast tissues and primary breast cancer lesions exhibiting higher expression than metastatic breast cancer lesions." (PMID 39189475, 2024). "To further demonstrate that PTPN14 knockout affected anoikis resistance in breast cancer cells, we analyzed changes in the expression of apoptosis‐related proteins in PTPN14‐KO and control cells under ULA conditions." (PMID 39189475, 2024). "To validate the changes in PTPN14 expression during breast cancer progression, we performed immunohistochemistry (IHC) analysis to compare PTPN14 expression in 11 normal breast tissues and 53 pairs of matched primary and metastatic breast cancer tissues." (PMID 39189475, 2024). "Collectively, these results provide evidence that BCAR3 is a phospho‐substrate for PTPN14 and that the function of PTPN14 in breast cancer anoikis and tumorigenicity involves BCAR3." (PMID 39189475, 2024). "PTPN9 overexpression suppressed invasion in breast cancer and PTPN14 overexpression correlates with decreased invasion in several cancer cell lines." (PMID 33710332, 2021). "PTPN14 knockdown in breast cancer cells or the intraperitoneal injection of mice with conditioned media from PTPN14-knockdown cells, promotes the growth and metastasis of breast cancer xenografts." (PMID 32152405, 2020). "In a xenograft breast cancer model, PTPN14 acts as a suppressor of metastasis of triple-negative breast cancer cells." (PMID 32536826, 2020). "In support of an alternate pathway, a recent study in breast cancer cells showed that PTPN14 can reduce the secretion of a suite of pro-metastatic factors by altering protein trafficking." (PMID 31806880, 2020). "In invasive ductal breast carcinomas, the expression of PTPN14 is lower (threefold) in comparison to ductal carcinomas, and the survival of breast cancer patients decreased if the tumors expressed high levels of the PTPN14 substrates, RIN1 or PKC-δ." (PMID 32152405, 2020).
breast carcinoma (continued). "Using a phospho-proteomic approach, potential novel substrates of PTPN14 were found, including breast cancer anti-estrogen resistance protein 1 (p130Cas)." (PMID 27240404, 2016). "While PTPN14 is mutated in a number of cancers, increased PRKCD and RIN1 expression correlated with decreased overall survival in breast cancer, with the PRKCD correlation significant in the luminal A subtype." (PMID 27240404, 2016). "In breast cancer, PTPN14 has the ability to inhibit metastasis through the alteration of protein trafficking." (PMID 27240404, 2016). "For example, in a xenograft breast cancer model, knockdown of PTPN14 in triple-negative breast cancer cells was able to promote invasiveness and metastasis." (PMID 27240404, 2016). "Importantly, we evaluated PTPN14 mRNA therapy in a spontaneous breast cancer metastasis model, highlighting its tumor‐suppressive effects and clinical translational potential." (PMID 39189475, 2024). "To investigate whether PTPN14 functions in breast cancer through BCAR3, we used siRNA specifically targeting BCAR3 to downregulate its expression in PTPN14‐KO and control cells." (PMID 39189475, 2024). "To further validate the impact of PTPN14 on the metastatic properties of breast cancer cells, particularly on anoikis resistance, we injected MDA‐MB‐231‐Luc (luciferase) cells overexpressing PTPN14 and their control counterparts into NOD SCID mice via the tail vein." (PMID 39189475, 2024). "Notably, PTPN14‐KO breast cancer cells showed higher phosphorylation levels of AKT Ser473 and ERK 1/2 than the control cells after 12 h of culture under ULA conditions." (PMID 39189475, 2024). "Knockdown of PTPN14 can promote the invasion and metastasis of breast cancer cells." (PMID 34712552, 2021). "PTPN14 was identified in a screen for PTPs that might function as tumor suppressors in breast cancer development." (PMID 27651363, 2016). "Negative regulation of YAP1 could explain the tumor suppressor functions of PTPN14, but in contrast, a recent publication showed that PTPN14 promotes aberrant cell growth in a breast cancer model." (PMID 27651363, 2016). "Therefore, we hypothesized that PTPN14 is likely to be a key gene involved in breast cancer anoikis resistance." (PMID 39189475, 2024). "In addition, knockout of PTPN14 promotes the growth and metastasis of breast cancer xenografts." (PMID 36106167, 2022). "PTPN14 negatively regulates the oncogenic function of yes-associated protein (YAP) by modulating the subcellular localization of YAP and suppressing its transcriptional co-activator activity, and also inhibits breast cancer metastasis by altering protein transport." (PMID 35957898, 2022). "Overexpressing PTPN14 inhibits anoikis resistance, tumorigenicity, and metastasis in TNBC cells by dephosphorylating breast cancer antiestrogen resistance 3, affecting the PI3K/AKT and ERK pathways." (PMID 39189475, 2024). "Taken together, these data indicate that alterations in the level of pY374-PKCδ, regulated by the opposing actions of the tyrosine kinase FER and the tyrosine phosphatase PTPN14, modulate EGFR signaling and the growth of breast cancer cells." (PMID 33411917, 2021). "Consistent with the tumor-suppressive role of these two miRNAs, TGFBR3 was reported to suppress breast cancer progression through TGF-beta signaling, and RBMS3 and PTPN14 were also shown to play roles in inhibiting metastasis." (PMID 32010179, 2019). "Breast cancer cells that express PTPN14 lacking catalytic activity show increased secretion of growth factors and cytokines and increased EGFR expression." (PMID 36106167, 2022). "However, most PTPN family members function as tumor suppressors in breast cancer, including PTPN2, PTPN4, PTPN6, PTPN9, PTPN13, PTPN14, and PTPN23." (PMID 35957898, 2022).
breast carcinoma (continued). "Alternatively, the silencing of PTPN14 in metastatic breast cancer cells that express [MDA-MB-231(shC)] or not CAV1 [MDA-MB-231(shCAV1)] using an esiRNA against PTPN14 increased cell migration, as well as invasion of those MDA-MB-231 cells expressing CAV1." (PMID 32152405, 2020). "In mammary epithelial cells, PTPD2 (PTPN14) is connected to erb-b2 receptor tyrosine kinase 2 (ERBB2) signaling, of which ERBB2 has been shown to be overexpressed or amplified in a portion of breast cancers and plays a role in tumorigenesis." (PMID 27240404, 2016). "The pathophysiological significance of the FER-PKCδ-PTPN14–mediated pathway we have identified is highlighted by our finding that high levels of pY374-PKCδ correlate with high levels of the RAB5-RAB7 transitional phenotype in triple-negative and HER2+ breast cancers." (PMID 33411917, 2021). "Contrary to the results observed in breast cancer cells, CCK‐8 and colony formation assays indicated that the overexpression of PTPN14 did not affect MCF10A cell proliferation." (PMID 39189475, 2024).
cervical cancer (9 papers, 2016 to 2025). A primary or metastatic malignant neoplasm involving the cervix. "PTPN14 loss-of-function variants were associated with high risks of cervical cancer and an early age at diagnosis." (PMID 36556168, 2022). "In a genome-wide sequencing study from Iceland, rare loss-of-function variants in PTPN14 were associated with high risk of cervical cancer (OR, 12.7, p = 1.6 × 10−4)." (PMID 34680286, 2021). "In high-risk HPV-infected cervical cancer cells, the protein level of endogenous PTPN14 was reported to be very low because of E7-mediated proteasomal degradation, consistent with our results." (PMID 31323018, 2019). "Thus, the high-risk HPV oncoproteins were necessary for the reduction of PTPN14 protein levels in cervical cancer cells, and based upon the effect of high-risk HPV E7 expression in the N/Tert-1 cells, we conclude that this resulted from an activity of the E7 oncoprotein." (PMID 27651363, 2016). "PTPN14, encoded a member of the protein tyrosine phosphatase (PTP) family, its mutation was considered to be associated with cervical cancer and be a high-impact basal cell carcinoma predisposition gene." (PMID 36450891, 2023). "High-risk E7 proteins target PTPN14 for proteasome-mediated degradation, which requires the ubiquitin ligase UBR4, and PTPN14 is degraded by the proteasome in HPV-positive cervical cancer cell lines." (PMID 27651363, 2016). "PTPN14 protein levels are low in HPV-positive cervical cancer cells and are restored upon depletion of the HPV E6/E7 early transcript." (PMID 27651363, 2016). "For example, PTPN14 negatively regulates the YAP pathway in cervical cancer and pancreatic cancer." (PMID 36898991, 2023). "This suggests that the protein–protein interaction site of PTPN14 could be a novel and suitable target for a therapeutic approach toward cervical cancer." (PMID 31323018, 2019). "To assess this hypothesis, we established stable HeLa cell lines constitutively expressing empty vector (mock), wild-type PTPN14, or the SQA mutant PTPN14 and investigated the effects of PTPN14 expression on cervical cancer cells." (PMID 31323018, 2019). "E7 is responsible for the upregulation of miR-21 in cervical cancer (56, –, 59), so the E7-induced increase in miR-21 could lead to a decrease in PTPN14 expression in E7-positive cells." (PMID 27651363, 2016). "To determine whether E7-mediated PTPN14 protein reduction also occurs in HPV-positive cervical cancer cell lines, we examined PTPN14 protein in HPV18-positive HeLa cell and HPV16-positive Caski cells." (PMID 27651363, 2016). "As per our earlier discussion, the role of PTPN14, CDK2 and HDAC9 in tumor suppression and the interaction with HPV E7 oncoprotein is observed stating that these targets can be potential druggable targets for cervical cancer." (PMID 35989375, 2022). "PTPN14 protein was not detectable in HeLa or Caski cells treated with nontargeting small interfering RNA (siRNA) but was readily detected in HPV-negative C33A cervical cancer cells." (PMID 27651363, 2016).
neuroblastoma (9 papers, 2015 to 2022). Neuroblastoma (NB) is the most common solid, extracranial childhood tumor. "Our results highlight a new role of PTPN14 in neuroblastoma migration and invasion and may represent a new diagnostic and/or therapeutic target for highly metastatic neuroblastoma." (PMID 31806880, 2020). "We next focused on 1p-intact neuroblastomas and studied the mutational spectrum of neuroblastoma candidate genes (particularly chromosome 1 genes CASZ1, CHD5, PTPN14, KIF1Bβ, NTRK1, and TP73), and their association with clinical prognostic variables." (PMID 35768791, 2022). "Mutations at PTPN14 gene have been found specifically in relapsed neuroblastoma tumors, suggesting the existence of an operative functional axis PTPN14-YAP in neuroblastoma relapse." (PMID 34957126, 2021). "PTPN14 has been shown to be involved in migration, invasion, and proliferation of neuroblastoma cells, as well as in the regulation of the nuclear translocation of the transcription coactivator YAP." (PMID 34957126, 2021). "In two independent neuroblastoma cells, suppression of PTPN14 expression led to an increase in cell migration and invasion." (PMID 31806880, 2020). "Further studies to understand the interrelationship between stathmin and PTPN14 expression and the migration/invasion phenotype in neuroblastoma are warranted." (PMID 31806880, 2020). "Focusing on one predicted target, we unrevealed a new function of the protein PTPN14 as an inhibitor of neuroblastoma cell migration and identified a potential new target for this metastatic disease." (PMID 31806880, 2020). "We focused on miR-382 and its predicted target gene PTPN14 and its relevance to neuroblastoma migration and invasion." (PMID 31806880, 2020). "To understand the role of PTPN14 on cellular functions in neuroblastoma cells, we used a gene-silencing approach in two independent neuroblastoma cell lines." (PMID 31806880, 2020). "Our findings demonstrate that stathmin levels can regulate PTPN14 expression, which can modulate neuroblastoma cell migration and invasion." (PMID 31806880, 2020). "Consistent with gene array data, PTPN14 mRNA and protein expression were downregulated in stathmin- depleted neuroblastoma cells and xenografts." (PMID 31806880, 2020). "To further elucidate the signalling pathway involving PTPN14 on neuroblastoma cells, we first investigated the impact of PTPN14 siRNA on stathmin expression." (PMID 31806880, 2020). "To determine its independent role in neuroblastoma, we depleted PTPN14 using siRNA in two independent neuroblastoma cell lines." (PMID 31806880, 2020). "Over the past few years, studies have accumulated relating PTPN14 to various cancer types including colorectal cancer, pancreatic cancer, neuroblastoma, and basal cell carcinoma." (PMID 27240404, 2016). "PTPN14 is a tyrosine phosphatase attributed in oncogenesis and is mutated in multiple cancer types while NR2C2 is known to protect neuroblastoma cells from chemotherapeutic drugs such as doxorubicin and etoposide." (PMID 25944692, 2015). "Our data suggest that PTPN14 expression could play a role in the aggressiveness of neuroblastoma and may provide potential new treatment strategies." (PMID 31806880, 2020). "In neuroblastoma, whole genome sequencing and gene set enrichment analysis (GSEA) in paired samples at diagnosis and relapse identified inactivating mutations in PTPN14 at relapse, along with a downregulation in genes known to be transcriptionally silenced by YAP." (PMID 27240404, 2016). "However, given the modest effect on YAP signalling, our findings also suggest that the effects of PTPN14 knockdown on neuroblastoma migration and invasion could be mediated by an alternative pathway." (PMID 31806880, 2020). "In neuroblastoma, STMN1 phosphorylation was reported to impact on metastasis by altering the levels of tyrosine-protein phosphatase non-receptor type 14 (PTPN14) or in a tubulin-independent manner to enhance transendothelial migration via RhoA/ROCK signaling." (PMID 34771457, 2021).